MIR582 (microRNA 582)
Synonyms: hsa-mir-582; MIRN582
Gene: MicroRNA gene on chromosome 5 (59,703,606 to 59,703,703, reverse strand). Ensembl gene ENSG00000202601.
Gene Ontology:
Biological process: miRNA-mediated post-transcriptional gene silencing
Cellular component: RISC complex
Homologues: Orthologues: chimpanzee ptr-mir-582 (100% identical), macaque mml-mir-582 (99% identical), guinea pig MIR582 (79% identical), dog MIR582 (78% identical), mouse Mir582 (78% identical), rat Mir582 (78% identical), pig ssc-mir-582 (76% identical), rabbit MIR582 (57% identical).